BRAF (B-Raf proto-oncogene, serine/threonine kinase)
Diseases named in the same sentence as BRAF in open-access papers (continued):
Sharing a sentence is not in itself a finding about the gene and the disease.
thyroid cancer (continued). "Studies have found that BRAF-mutant thyroid cancers exhibit enhanced metabolic reprogramming and aggressive characteristics." (PMID 41301693, 2025). "BRAF V600E as the most common alteration in thyroid cancer is used in the targeted treatment of thyroid cancer." (PMID 39940256, 2025). "It marks a paradigm shift, establishing BRAF-targeted therapy as a cornerstone in the modern management of thyroid cancer." (PMID 41368991, 2025). "Clinical outcomes specific to thyroid cancer were later reported in a dedicated subanalysis of a phase I trial including 14 patients with BRAF V600E-mutant metastatic thyroid carcinoma, of whom 93% had received prior radioactive iodine." (PMID 41368991, 2025). "In summary, HIF-1α, BRAF mutations, and TSHR signaling synergistically contribute to metabolic plasticity in thyroid cancer, representing key mechanisms underlying metabolic reprogramming and drug resistance." (PMID 41301693, 2025). "Similar to other malignancies, the emergence and advancement of thyroid cancer are accompanied by genetic mutations, such as RAS, BRAF, or TERT mutations, as well as RET and NTRK rearrangements." (PMID 40586006, 2025). "Understanding the role of BRAF mutations in PTC is essential for improving diagnostic accuracy, treatment strategies, and patient outcomes in thyroid cancer management." (PMID 39744583, 2025). "As for immunotherapy, PD-1/PD-L1 inhibitors, such as pembrolizumab and nivolumab, are being investigated in combination with other targeted therapies, like BRAF inhibitors, to improve the immune response in patients with refractory thyroid cancer." (PMID 39744583, 2025). "Three of them, selumetinib, vemurafenib, and dabrafenib, have been clinically tested in BRAF-mutant thyroid cancer patients." (PMID 41368991, 2025). "Specifically, both tumor antigens should be considered when designing future clinical trials for ATC patients with BRAF wild-type tumors or patients with advanced thyroid cancers relapsed/refractory to first line target therapies." (PMID 40847369, 2025). "This approach has already facilitated the development of targeted therapies, such as inhibitors for BRAF and RET mutations, which are commonly implicated in thyroid cancer." (PMID 40297138, 2025). "Combination therapies and targeted approaches are being investigated to address drug resistance and enhance the efficacy of BRAF inhibitor treatment in patients with thyroid cancer." (PMID 40129883, 2025). "In conclusion, the authors suggest that targeting NG2 represents a promising strategy to overcome resistance to BRAF inhibitors in BRAFV600E-driven thyroid cancer." (PMID 39874138, 2025). "The unraveling of the therapeutic role of BRAF in advanced thyroid cancer followed a successful process of translational research." (PMID 41368991, 2025). "Dabrafenib plus trametinib combination therapy demonstrated clinical effectiveness in patients with BRAF V600E-positive thyroid cancer, with response rates comparable to those observed in clinical trials." (PMID 40844731, 2025).
thyroid cancer (continued). "Previous studies have shown that resistance to BRAF kinase inhibitors in BRAF-mutant thyroid cancer is due to the reactivation of the MAPK/ERK and PI3K/AKT pathwa." (PMID 40063000, 2025). "This study describes the real-world efficacy and safety of dabrafenib and trametinib combination therapy in patients with BRAF V600E-positive thyroid cancer in Japan." (PMID 40844731, 2025). "The identification of driver mutations that activate this pathway, such as BRAF, RAS mutations and RET/PTC rearrangements, has provided critical insights into thyroid cancer biology and facilitated the development of targeted therapies." (PMID 39874138, 2025). "After BRAF, activating mutations of RAS (NRAS >> HRAS > KRAS) are the next most common oncogenic drivers found in advanced thyroid cancers." (PMID 39874138, 2025). "To specifically study nuclear FAK in cells devoid of endogenous FAK, we generated a FAK knockout (FAK-KO) model in the BRAF-mutant BCPAP thyroid cancer cell line using CRISPR/Cas9." (PMID 40458728, 2025). "This case report illustrates a misdiagnosed primary thyroid cancer which was later identified as an atypical metastasis of BRAF V600E-mutant lung adenocarcinoma." (PMID 39980562, 2025). "BRAF and RAS gene mutations are core drivers of thyroid cancer; they are generally mutually exclusive and induce varying degrees of MAPK pathway activation." (PMID 41462994, 2025). "This approach identified significant dependencies on key genes/proteins such as KRAS, NRAS, PABPC1, PPP2R1A, STAG2, and BRAF in thyroid cancer cell lines, underscoring their potential as critical therapeutic targets." (PMID 40297138, 2025). "In the analysis of BRAF V600E gene expression, the expression of the BRAF V600E gene in thyroid cancer cells in the 3D scaffold group was significantly higher than in the 2D group." (PMID 41311976, 2025). "Indeed, the results of a pilot clinical trial using a MAPK inhibition redifferentiation strategy in patients with BRAF p.V600E radioiodine-refractory thyroid carcinoma suggests that SWI/SNF gene mutation may be a marker of resistance to these forms of treatment." (PMID 41175860, 2025). "For other genes including BRAF, strong performance was confined to limited tumour types, particularly thyroid carcinoma and cutaneous melanoma." (PMID 40775769, 2025). "For BRAF, where the model performed well only in thyroid carcinoma and cutaneous melanoma, balancing the underperforming tumour types improved performance considerably in colorectal and stomach adenocarcinomas." (PMID 40775769, 2025). "Perhaps BRAF V600E AF becomes a significant contributor to ETE only in the presence of synergistic factors to thyroid carcinoma progression, such as aggressive histological subtype and lymph node metastases." (PMID 40805249, 2025). "The therapeutic potential of the DNA ligase IV inhibitor should need further validation on thyroid cancer cell lines characterized by different cancer genetic drivers (e.g. BRAF p.V600, NRAS p.Q61K)." (PMID 38380364, 2024). "ALK fusions were predominantly observed in lung cancer and lymphoma, while RET, ABL1, and BRAF fusions have been identified most frequently in thyroid cancer, leukemias, and pediatric low-grade gliomas, respectively." (PMID 38877018, 2024). "NG2 knockout attenuates the PLX4720-mediated feedback activation of several RTKs, improving the sensitivity of BRAF-mutant thyroid cancer cells to this inhibitor." (PMID 38795180, 2024). "Several studies have raised the possible mechanisms of the resistance to BRAF inhibitors in BRAF-mutant thyroid cancers." (PMID 38795180, 2024). "This study highlights the correlation between thyroglobulin and calcitonin levels, the presence of the BRAF gene, and the disease stage, especially regarding thyroid cancer diagnosis and prognosis." (PMID 39767732, 2024).
thyroid cancer (continued). "Although its inhibitors dabrafenib and vemurafenib have demonstrated potential therapeutic efficacy for BRAF-mutant thyroid cancers, their widespread utilization in clinical practice has been limited partly due to the emergence of drug resistance." (PMID 38795180, 2024). "To determine which RTKs participate in NG2-mediated resistance of BRAF-mutant thyroid cancer cells to BRAF inhibitor, we established NG2-knockout 8505 C cell- and control cell-derived xenograft mouse models, and treated them with PLX4720 (20 mg/kg)." (PMID 38795180, 2024). "Overall, combined AURKB and MEK1/2 inhibition decreases cell growth 64–87%, suggesting a potential benefit of combined MEK1/2 and AURKB inhibition in BRAF-mutant thyroid cancer cell lines." (PMID 38521968, 2024). "For these studies, BRAF-mutant thyroid cancer cells were treated with vehicle, MEKi, the AURKB inhibitor, barasertib (AURKBi), or the combination, for 72 hrs and counted using automated counting." (PMID 38521968, 2024). "Overall, the combination of BRAF inhibitor dabrafenib and MEK inhibitor trametinib can offer excellent outcomes in selected BRAF V600E-mutated thyroid cancer patients, either with ATC or PTC." (PMID 39064466, 2024). "Redifferentiation therapy has shown promising results beyond tumors with BRAF and RAS mutations, demonstrating potential efficacy in thyroid cancers with various other genetic alterations." (PMID 39685478, 2024). "BRAF gene rearrangement (AKAP9-BRAF) is more common in radiation-related PTC but has also been reported in poorly differentiated thyroid cancers and anaplastic thyroid cancers." (PMID 39473507, 2024). "Together, these data suggest inhibition of AURKB in combination with a MAPK-directed therapy is a promising target for BRAF-mutant thyroid cancer." (PMID 38521968, 2024). "For example, BRAF V600E and RAS mutations are the main genetic drivers in thyroid cancers, followed by fusions involving RET and other receptor tyrosine kinases." (PMID 38504322, 2024). "Based on this finding, we propose and demonstrate an alternative strategy for targeting NG2 to effectively treat BRAF-mutant thyroid cancers by combining multiple kinase inhibitor (MKI) Sorafenib or Lenvatinib with PLX4720." (PMID 38795180, 2024). "CGI indicated that (i) BRAF is a known oncogene driver in this cancer; (ii) V600E is a common mutation seen in many types of cancers (including thyroid carcinoma); and (iii) there are several approved targeted therapies for BRAF-mutant thyroid cancer." (PMID 38304083, 2024). "Four of these mutations (BRAF, RET, RET/PTC, andNTRK3) possess targeted therapies that have been approved in thyroid cancers." (PMID 39235852, 2024). "At present, studies have shown that mutations, including fusions, involving the BRAF and RET genes are associated with a higher likelihood of a clinical diagnosis of thyroid cancer." (PMID 39558959, 2024). "According to these observations, we propose an alternative strategy for targeting NG2 to treat BRAF-mutant thyroid cancers by combining Sorafenib or Lenvatinib with BRAF inhibitor." (PMID 38795180, 2024). "Common genetic alterations found in thyroid cancer include BRAF V600E, NRAS, HRAS, KRAS, RET/PTC, and TERTp." (PMID 39456540, 2024). "Among the study population, nine patients harbored BRAF V600E mutations, three had NRAS mutations, and one patient had wild-type thyroid cancer." (PMID 39685478, 2024). "The PI3K/Akt/mTOR pathway is primarily activated at different targets in diseases with BRAF and RAS mutations, and these specific combinations have been shown to induce thyroid cancer progression in mouse models." (PMID 38275415, 2024). "We first showed that combined BRAF and MEK1/2 inhibition synergistically inhibits cell growth in four out of six of the ­BRAF-mutant thyroid cancer cell lines tested." (PMID 38521968, 2024).
thyroid cancer (continued). "Together, these data suggest that combined AURKBi and ERKi-SCH induces apoptotic cell death in BRAF-mutant thyroid cancer cells." (PMID 38521968, 2024). "Overexpression of HMGB1 has been shown to reduce the sensitivity of BRAF(V600E) mutant thyroid cancer cells to Vemurafenib by increasing cell viability and decreasing apoptosis and caspase-3 activity." (PMID 39052013, 2024). "For instance, BRAF-V600E serves as a diagnostic cornerstone across multiple pathological subtypes of thyroid cancer and correlates with the therapeutic effectiveness of BRAF inhibitors such as vemurafenib and dabrafenib." (PMID 38403820, 2024). "In this process, NG2 acts as an important player in reactivating RTK signaling, as supported by our data showing that NG2 knockout relieves the feedback activation of RTKs and improves the response of BRAF-mutant thyroid cancer cells to BRAF inhibitor." (PMID 38795180, 2024). "Clinical studies for new BRAF inhibitors and combination therapy are now underway, adding to the developing landscape of precision medicine in thyroid cancer." (PMID 38501105, 2024). "Here, we identified an induction of Aurora kinase B (AURKB) in response to MEKi in BRAF-mutant thyroid cancer cells that are resistant to combined BRAF/MEK1/2 inhibition." (PMID 38521968, 2024). "Thyroid cancer, particularly papillary thyroid cancer patients with a poor prognosis, can also be caused by TERT promoter (TERTp) mutations in conjunction with BRAF mutations." (PMID 38819232, 2024). "Functional studies show that NG2 knockout almost does not affect tumor growth, but significantly improves the response of BRAF-mutant thyroid cancer cells to BRAF inhibitor PLX4720." (PMID 38795180, 2024). "In thyroid cancer, increased DUSP5 and DUSP6 MAPK phosphatase expression was associated with higher ERK activity in BRAF-mutant tumors." (PMID 39436655, 2024). "Lapatinib as a small molecule dual tyrosine kinase inhibitor of EGFR and HER-2 has been demonstrated the ability to prevent the rebound of the ERK signaling and sensitize BRAF-mutant thyroid cancer cells to RAF or MEK inhibitors." (PMID 38795180, 2024). "In thyroid cancer, alterations in this pathway can occur at different levels due to point mutations or rearrangements involving the RAS and BRAF genes." (PMID 38920735, 2024). "Multikinase inhibitors, such as sorafenib and lenvatinib, have been used successfully to treat thyroid carcinoma, and specific inhibitors for genetic abnormalities acquired early, such as BRAF, RET, and NTRK alterations, are effective." (PMID 38630010, 2024). "Genetic mutations, such as within the BRAF gene, have been observed in cases of OTC with cervical nodal metastasis, along with other types of thyroid carcinomas as well." (PMID 39070383, 2024). "A number of mutations and compensatory mechanisms have been observed to mediate bypass of BRAF blockade by thyroid carcinoma cells." (PMID 38275291, 2024). "The treatment of advanced thyroid carcinomas as PDTC and ATC with BRAF inhibitor dabrafenib and MEK inhibitor trametinib have shown significant redifferentiation and response rates in BRAF-mutated tumors." (PMID 37985676, 2024). "Treating thyroid cancer cells with BRAF inhibitors will set free C-terminal binding proteins (CTBPs), which was revealed as important transcription factors to promoting expression of HER3." (PMID 36624452, 2023). "The most frequently associated genes with thyroid cancer found on PubMed were BAX, XRCC1, XRCC3, XPO5, IL-10, BRAF, RET, and K-RAS." (PMID 37211566, 2023).
thyroid cancer (continued). "In conclusion, we have identified and characterized a Cre/loxP-based mouse model that allows independent investigation of sporadic lung and thyroid cancer that largely mimic the features of BRAF-driven NSCLC and PTC in humans." (PMID 37534159, 2023). "The aim of this study was to explore EGFR, CD44v6 and BRAF as molecular targets in thyroid cancer by assessing patient samples from PFC, FTC and ATC, as well as in cultured thyroid cancer cell lines." (PMID 38076095, 2023). "Combined with Ref-1 inhibitor, it can also make BRAF-mutant thyroid cancers more sensitive to vemurafenib by inhibiting the MAPK/ERK pathway." (PMID 36834830, 2023). "It has been demonstrated that the dual EGFR/HER-2 kinase inhibitor lapatinib sensitizes BRAF-mutant thyroid cancers to BRAF kinase inhibitors by blocking the rebound of MAPK/ERK pathway and the activation of the PI3K/AKT pathway." (PMID 36834830, 2023). "Vitamin C has been found to sensitize BRAF V600E thyroid cancer to PLX4032, a targeted therapy, by relieving the feedback activation of MAPK/ERK and PI3K/AKT pathways." (PMID 37246589, 2023). "Driver mutations are identifiable in >90% of all thyroid cancers, with the most common driver mutations in advanced thyroid cancer patients being mitogen-activated protein kinase, herein referred to as MAPK, pathway mutations in either BRAF or RAS." (PMID 36672327, 2023). "A total of 90% of thyroid cancers have identifiable driver mutations, which often are components of the MAPK pathway, including BRAF, RAS, and RET-fusions." (PMID 36672327, 2023). "Given that MEK is downstream from BRAF and given positive data for Selumetinib in BRAFV600E mutated thyroid cancer cell lines, a phase II clinical trial with RAIR patients was initiated." (PMID 38255638, 2023). "As previously discussed in the molecular biology section, BRAF mutations dysregulate the capacity of follicular cells for iodine uptake and in fact BRAFV600E mutant thyroid cancers are often refractory to RAI." (PMID 38255638, 2023). "Radiomics have been explored in the field of thyroid cancer research, such as benign and malignant diagnosis of thyroid nodules, prediction of CLNM, extrathyroidal invasion of thyroid cancer, BRAF-V600E gene mutation and survival prediction." (PMID 37361586, 2023). "In summary, activating the SHH pathway through mutations in the RAS/BRAF/MEK pathway and the presence of paracrine factors in the interstitial space of thyroid cancer cells can enhance GLI1 expression and activity." (PMID 38313845, 2023). "The p27 modulation is in agreement with the already described reduction of p27 levels upon expression of RAS, BRAF or RET/PTC mutants in thyroid cancer cells, which would be reversed by MEK inhibition." (PMID 37964967, 2023). "Mechanistically, DSF/Cu sensitizes BRAF-mutant thyroid cancer cells to PLX4032 by inhibiting HER3 and AKT in an ROS-dependent way and subsequently relieving feedback activation of MAPK/ERK and PI3K/AKT pathways." (PMID 36834830, 2023). "Taken together, STRA6 is upregulated in thyroid cancer and exhibits extremely higher expression in BRAF-mutant PTC." (PMID 36843593, 2023). "In the present study, we found that most of the RTK receptors and ligands were activated during the treatment of thyroid cancer cells with the BRAF inhibitor vemurafenib, while SHP2, a key protein downstream of the RTK signaling pathway, was also activated." (PMID 37325052, 2023). "In summary, our results provide insights into β-catenin signaling in the NK cell-mediated immune response against BRAF-mutant thyroid cancer cells." (PMID 37483610, 2023). "The reactivation of HER family members (HER2/HER3) induced the relieving of MAPK/ERK pathways inhibition, leading to the resistance towards BRAF inhibitors in thyroid cancer cells." (PMID 36624452, 2023). "RAF inhibitors have a vital role in treating thyroid cancer, and the efficiency of RAF inhibitors is associated with BRAF status." (PMID 36646686, 2023).